IRF2BP2 (interferon regulatory factor 2 binding protein 2)
Diseases named in the same sentence as IRF2BP2 in open-access papers (continued):
Sharing a sentence is not in itself a finding about the gene and the disease.
adenomyosis (1 paper, 2025). The growth of endometrial tissue inside the muscular wall of the uterine corpus. "Conversely, the analysis predicted a notable activation of the upstream regulators MAPK1, IRF2BP2 and multiple microRNAs in internal adenomyosis compared to external adenomyosis." (PMID 40531845, 2025). "Upstream regulator analysis predicted the activation of inflammatory mediators like LPS, TGF-β1, IL-4, and IFN-γ in external adenomyosis, and MAPK1 and IRF2BP2 along with multiple microRNAs in internal adenomyosis." (PMID 40531845, 2025).
Adult onset (1 paper, 2022). Onset of disease manifestations in adulthood, defined here as at the age of 16 years or later. "However, since Irf2bp2-positive lymphoblasts are not detected in Irf2bp2-null mice, these chimeric mice are not protected from adult-onset lymphoma caused by loss of Irf2bp2." (PMID 35865523, 2022).
Arthritis (1 paper, 2025). Inflammation of a joint. "Despite the absence of serological markers for rheumatoid arthritis, some patients with IRF2BP2 deficiency exhibited arthritis progression to destructive disease." (PMID 41246352, 2025). "A recent report described that individuals with IRF2BP2 variants develop immunodeficiency, frequently accompanied by inflammatory diseases, aligning with our patient who presented with CVID and systemic inflammation, including PBC and unclassified arthritis." (PMID 41246352, 2025).
breast tumors (1 paper, 2020). "We next sought to address the correlation between CNA frequencies and expression levels of MYC, EGFR, ASAP1, IRF2BP2, CCT5, and DRD1 in broad BC cell lines and breast tumors and the clinical relevance of the genes to patients with BC." (PMID 32235890, 2020). "While CNA events in deep or shallow depletion rarely or less occurred, EGFR, MYC, IRF2BP2, ASAP1, and CCT5 (except for DRD1) often underwent copy gain and amplification, acquiring CNA-driven expression in the breast tumors." (PMID 32235890, 2020).
cardiomyopathy (1 paper, 2021). A disease of the heart muscle or myocardium proper. "In this study, IRF2BP2 was found to protect the heart from LPS-induced inflammation and cardiomyopathy." (PMID 34760935, 2021).
diabetes (1 paper, 2025). "IRF2BP2 mRNA levels were slightly (~20%) but significantly decreased in adipose tissue from patients with diabetes, compared to nondiabetic individuals." (PMID 39752494, 2025).
endometriosis (1 paper, 2024). The growth of functional endometrial tissue in anatomic sites outside the uterine body. "There were 12 molecules that returned no search results on PubMed, including the transcription regulators IRF2BP2, TBX2 and ZBTB10, suggesting that these endogenous molecules could have as yet unidentified roles in the establishment of endometriosis lesions." (PMID 39385609, 2024).
enteropathy (1 paper, 2023). "Regarding phenotype, patient 2.1, carrier of a de novo insertion (p.Ala110Argfs*48), suffered Crohn’s like enteropathy treated for a long time with anti-TNF therapy, and represents a good example of enteropathy associated with IRF2BP2-CVID." (PMID 37876937, 2023).
Glucose intolerance (1 paper, 2025). Glucose intolerance (GI) can be defined as dysglycemia that comprises both prediabetes and diabetes. "Adipocyte-selective deletion of Irf2bp2 in mice increases Lipe expression and free fatty acid levels, resulting in adipose tissue inflammation and glucose intolerance." (PMID 39752494, 2025). "Consequently, Irf2bp2 mutant mice exhibit increased adipose tissue and systemic inflammation and glucose intolerance." (PMID 39752494, 2025).
Immunodeficiency (1 paper, 2025). Failure of the immune system to protect the body adequately from infection, due to the absence or insufficiency of some component process or substance. "This case underscores the phenotype of IRF2BP2-related immunodeficiency with concomitant B- and T-cell dysregulation caused by a novel IRF2BP2 variant." (PMID 41246352, 2025).
Insulin resistance (1 paper, 2025). Increased resistance towards insulin, that is, diminished effectiveness of insulin in reducing blood glucose levels. "In line with this, adipocyte Irf2bp2 deficiency led to adipose tissue inflammation and systemic insulin resistance in the absence of high-fat diet or weight gain." (PMID 39752494, 2025).
lymph node metastasis (1 paper, 2019). "Given that IRF2BP2 expression was correlated with lymph node metastasis and vascular invasion in clinical samples, a transwell assay was performed to investigate the role of IRF2BP2 in migration and invasion." (PMID 31559693, 2019). "IRF2BP2 expression was closely associated with age (P = .036), tumour size (P = .0006), TNM stage (P = .0002), depth of invasion (P = .0002), lymph node metastasis (P = .0008) and vascular invasion (P = .03)." (PMID 31559693, 2019).
lymphoma (1 paper, 2022). A malignant (clonal) proliferation of B- lymphocytes or T- lymphocytes which involves the lymph nodes, bone marrow and/or extranodal sites. "The presence of lymphoma in Irf2bp2-deficient/chimeric mice was noteworthy because it suggests that loss of Irf2bp2 facilitates this process." (PMID 35865523, 2022). "As in humans with somatic mutations in IRF2BP2, adult Irf2bp2-null mice developed lymphoma." (PMID 35865523, 2022). "Lymphoma was a prevalent phenotype of adult Irf2bp2-null mice over the age of 6 months in both male and female mice; upon sacrifice, mice displayed an enlarged spleen and liver." (PMID 35865523, 2022). "It is also noteworthy that the cluster of lymphocytes (infiltrating lymphoma, asterisk) in the Irf2bp2 null liver was Irf2bp2 negative." (PMID 35865523, 2022).
mesenchymal neoplasms (1 paper, 2025). "We identified three tumors in our epigenetically distinct METs group that carried fusions described in molecularly defined, non-MET tumor types, i.e., EWSR1::NFATC2-rearranged mesenchymal neoplasms and IRF2BP2::CDX1-rearranged neoplasm." (PMID 39636306, 2025).
Obesity (1 paper, 2021). Accumulation of substantial excess body fat. "Irf2bp2 is a key regulator of the inflammatory response in macrophages and microglial cells by affecting the polarization; thus, these data indicate a possible neuroprotective role of Irf2bp2 in obesity." (PMID 33808700, 2021).
osteoporosis (1 paper, 2021). A condition of reduced bone mass, with decreased cortical thickness and a decrease in the number and size of the trabeculae of cancellous bone (but normal chemical composition), resulting in increased fracture incidence. "More recently, a single nucleotide polymorphism (SNP), rs6672925, that lies just 3′ of the IRF2BP2 gene was found to associate with osteoporosis in two large genome-wide association studies (GWAS)." (PMID 34760935, 2021). "Thus, reduced expression of IRF2BP2 tied to the rs3045215 deletion may explain why individuals who carry the co-inherited SNP rs6672925 have increased susceptibility to osteoporosis." (PMID 34760935, 2021).
primary central nervous system lymphoma (1 paper, 2021). A non-Hodgkin or Hodgkin lymphoma that arises in the brain or spinal cord as a primary lesion. "Mutations in the IRF2BP2 gene have also been identified in primary central nervous system lymphoma (PCNSL)." (PMID 33996817, 2021).
primary immunodeficiency (1 paper, 2023). "In this study, we report five novel variants in IRF2BP2 likely responsible of primary immunodeficiency, four of them were frameshift mutation and one a large CNV." (PMID 37876937, 2023). "The results of this study were possible thanks to collect the data from 5 years of experience analyzing IRF2BP2 in patients with primary immunodeficiency." (PMID 37876937, 2023). "Before this study, only five families with CVID caused by defects in IRF2BP2 had been published, now, we add five families from Spain with five novel truncating variants, which suggests that this gene may be undertested in the context of primary immunodeficiency and inflammatory conditions." (PMID 37876937, 2023).
squamous cell carcinoma (1 paper, 2025). A carcinoma arising from squamous epithelial cells. "This is particularly relevant in cases where RUNX2 rearrangements or IRF2BP2::RUNX2 fusion have been identified, as seen in studies of primary squamous cell carcinoma of the parotid, where certain cases were later reclassified as keratocystoma or squamous cell carcinoma ex-keratocystoma." (PMID 40217739, 2025).
vasculitis (1 paper, 2014). "The HCV MC vasculitis cohort had greater gene expression of IRF2BP2 when compared to the other study groups [2.10 ± 0.90 (NV), 5.10 ± 0.80 (HCV MC-Vasc), 3.10 ± 0.90 (HCV), 3.40 ± 0.80 (HIV/HCV); p = 0.03 between HCV MC-Vasc and HCV viremic]." (PMID 24904592, 2014).
tumor (13 papers, 2012 to 2025). "Functionally, SPOP enables inhibition of the anti-tumor role of IRF2BP2 in HCC cells, which is eliminated by mutating the SBC motif in IRF2BP2." (PMID 38409107, 2024). "Through next-generation sequencing, tumor samples were subjected to mutational profiling, and an in-frame gene rearrangement involving IRF2BP2 exon 1 and NTRK1 exons 8–16 was identified." (PMID 33996817, 2021). "IRF2BP2‐deficient tumor cells showed suppressed growth in NSG mice." (PMID 39454110, 2024). "Therefore, the IHC results suggest that the expression of IRF2BP2 is positively associated with tumour progression and poor prognosis in patients with GC." (PMID 31559693, 2019). "We next sought to test whether tumor-derived mutations affect SPOP interactions with IRF2BP2." (PMID 38409107, 2024). "This system enables responsive drug release in the acidic tumor microenvironment and co-delivers a miR-620 inhibitor to suppress the IRF2BP2 axis, resulting in dual inhibition of tumor cell proliferation and induction of apoptosis." (PMID 41149588, 2025). "Histologically, both tumors with IRF2BP2::CDX1 rearrangement (cases 8–9) showed a well-circumscribed lesion composed of bland epithelioid tumor cells in a chondromyxoid stroma." (PMID 39636306, 2025). "Consistently, H.E. staining and immunohistochemical analysis for Ki67 and c‐Myc demonstrated reduced tumor infiltration in the liver, spleen, and bone marrow following IRF2BP2 knockdown." (PMID 39454110, 2024). "Although growing studies have revealed the important anti-tumor role of IRF2BP2 in various cancers, the mechanisms for governing its abundance are still unclear." (PMID 38409107, 2024). "The IRF2BP2 protein is found in different organisms and has been described as ubiquitously expressed in normal and tumor cells and tissues, indicating a possible role for this transcriptional cofactor in different cell signaling pathways." (PMID 33996817, 2021). "In this review, we address the possible involvement of IRF2BP2 in tumorigenesis through its regulation of important pathways involved in tumor development." (PMID 33996817, 2021). "IRF2BP2 depletion led to enhanced cell growth and colony formation and promoted HepG2 xenograft tumor growth." (PMID 33996817, 2021). "Taken together, these results showed that IRF2BP2 exhibits tumor-suppressor activity in the liver, inhibiting liver cancer cell growth and tumor formation." (PMID 33996817, 2021). "Based on the importance of NFAT1 in the immune response and tumor cells, it is crucial to elucidate the repressor mechanisms mediated by IRF2BP2." (PMID 33996817, 2021). "This review focuses on the involvement of IRF2BP2 in tumorigenesis through the regulation of important pathways in tumor development." (PMID 33996817, 2021). "In this tumor model, loss of Cdk5 results in persistent expression of IRF2 and IRF2BP2, which likely leads to reduced PD-L1 expression on tumors thereby promoting anti-tumor immunity." (PMID 35582274, 2019). "The Cancer Genome Atlas (TCGA) database shows the amplification of the IRF2BP2 gene in the majority of malignant tumours, including GC, which prompted us to focus on the clinical significance and roles of IRF2BP2 in human GC." (PMID 31559693, 2019). "The presence of the IRF2BP2-CDX1 fusion gene was tested for in specimens from tumour 2–4 using primer combinations IRF2BP2-926F and CDX1-771R." (PMID 23185413, 2012). "In vivo imaging indicated significantly lower tumor cell signals in the IRF2BP2‐knockdown group." (PMID 39454110, 2024). "In this study, we find the tumor suppressor IRF2BP2 as a novel substrate of SPOP." (PMID 38409107, 2024). "Given that SPOP binds the SBC in IRF2BP2, we next examined whether disruption of the interaction boots IRF2BP2’s anti-tumor activity." (PMID 38409107, 2024).
tumor (continued). "Based on these, we propose the hypothesis that M35L mutation possibly exchanges SPOP substrates from oncoproteins (such as GLI2, c-MYC and TRIM24) to tumor suppressors (such as IRF2BP2), therefore reprogramming the tumor properties of SPOP." (PMID 38409107, 2024). "In this study, we identify the tumor suppressor IRF2BP2 as a novel substrate of SPOP." (PMID 38409107, 2024). "Interestingly, the IRF2BP2::NTRK1 containing tumour was the only one located to the left colon (sigma) amongst our NTRK1 fusion–positive cases." (PMID 35237889, 2022). "The results suggest that the knockdown of IRF2BP2 significantly inhibits tumour growth." (PMID 31559693, 2019). "It important to note that, the differences in cellular proliferation phenotypes observed in previous studies may be associated with the different interaction partners and/or target genes of the IRF2BP2, which may be involved with the type of cell and tumor involved." (PMID 33996817, 2021). "Additionally, GC cells expressing IRF2BP2 shRNA were inoculated subcutaneously in mice to construct xenograft models, and the results showed that knocking down IRF2BP2 significantly inhibited tumor growth." (PMID 33996817, 2021). "IRF2BP2 stabilized VGLL4 protein and repressed tumor progression via the inactivation of YAP-TEAD4 complex in liver cancer." (PMID 32793503, 2020). "It has also been reported that IRF2BP2 and VGLL4 promote tumor growth through the induction of the immune checkpoint protein programmed cell death-ligand 1 (PD-L1) and immune evasion of tumor cells." (PMID 32793503, 2020). "However, overexpression of IRF2BP2 alone also inhibited HCC cell proliferation and migration, reflecting its anti-tumor role." (PMID 38409107, 2024). "In contrast, IRF2BP2 expression is significantly elevated in T‐ALL cells compared to normal T cells, where it plays a critical role in supporting the growth and survival of tumor cells." (PMID 39454110, 2024).
cancer (8 papers, 2012 to 2025). A tumor composed of atypical neoplastic, often pleomorphic cells that invade other tissues. "Together, these findings indicate roles for IRF2BP2 in the cancer immune response and cancer response, and this association must be elucidated." (PMID 33996817, 2021). "Intriguingly, IRF2BP2-specific target genes show strong associations with biological processes and functions involved in survival, apoptosis and cancer." (PMID 26593974, 2015). "Compared with normal liver cells, SPOP-M35L shows a stronger affinity to IRF2BP2 in cancer cells, leading to the upregulation of cell proliferation and migration." (PMID 38409107, 2024). "Some studies have reported the participation of IRF2BP2 in the development of different kinds of cancer through gene fusion, copy number variations and mutations." (PMID 33996817, 2021). "Interferon regulatory factor 2-binding protein 2 is extensively involved in regulating gene expression and other biological processes, including metabolic syndrome, nervous diseases, immunodeficiency disorders, and cancer." (PMID 33996817, 2021). "Therefore, discovery of certain drug targets GFI1 for proteasomal degradation by IRF2BP2 might be an effective anti-cancer strategy." (PMID 34351909, 2021). "However, an imbalance in IRF2BP2 function may be related to the pathophysiology of cancer." (PMID 33996817, 2021). "IRF2BP2 knockdown in HeLa cells led to an upregulation of EGFR which may contribute to enhanced proliferation in response to EGF, a potent regulator of cellular growth as well as in cancer progression." (PMID 33996817, 2021).
infection (1 paper, 2017). The state of being infected such as from the introduction of a foreign agent such as serum, vaccine, antigenic substance or organism. "Furthermore, PTGS2 involved in the production of anti-inflammatory prostaglandins was also induced upon infection, with possible negative roles upstream and downstream of blocking IFN-STAT1-IRF activation pathways, while IRF2BP2 a potent repressor of innate inflammation was not." (PMID 28993767, 2017).
metabolic disease (1 paper, 2025). A congenital disorder (due to inherited enzyme abnormality) or acquired (due to failure of a metabolically important organ) disorder resulting from an abnormal metabolic process. "Together, these findings demonstrate that IRF2BP2 restrains adipocyte lipolysis and opens avenues to target lipolysis for the treatment of metabolic disease." (PMID 39752494, 2025).
IRF2BP2 also shares sentences with these, for which no sentence is quoted: neuroblastoma (3 papers); immune system diseases (2); pancreatic cancer (2); Adult T-cell leukemia (1); asthma (1); atopic dermatitis (1); autoimmune disease (1); autoimmune disorders (1); brain injury (1); chronic lymphocytic thyroiditis (1); colorectal cancer (1); coronary artery calcification (1); coronary artery disease (1); Crohn disease (1); E. coli infection (1); endometrial cancer (1); gastrointestinal infections (1); heart disease (1); lung carcinoma (1); lymphopenia (1); metastatic disease (1); multiple myeloma (1); multiple sclerosis (1); osteosarcoma (1); parasitemia (1); primary biliary cholangitis (1); respiratory infections (1); rheumatoid arthritis (1); thyroid cancer (1).